PLD1 (phospholipase D1)
Diseases named in the same sentence as PLD1 in open-access papers (continued):
Sharing a sentence is not in itself a finding about the gene and the disease.
ischemic stroke (4 papers, 2016 to 2024). A stroke disorder caused by obstruction of blood flow to the brain, due to thrombotic (local blood clot formation) or embolic (due to a blood clot or other material traveling from another site) event. "In a study of ischemic stroke, selective inhibition of PLD1 substantially reduced infarct area and cerebral edema in mice, leading to improved neurological function scores." (PMID 38572075, 2024). "Therefore, in the present study, we further used two different thrombotic models of acute pulmonary thrombosis and ischemic stroke, to define the roles of PLD1 and PLD2." (PMID 32971863, 2020). "Treatment of platelets and mice with the PLD inhibitor FIPI (5-Fluoro-2-Indolyl Deschlorohalopemide) known to inhibit the enzymatic activity of both PLD1 and PLD2 resulted in altered platelet activation and protection against FeCl3 injury and ischemic stroke as observed in Pld1-/-/Pld2-/-mice." (PMID 30555342, 2018). "Here, we confirmed that PLD1 might play more important roles than PLD2 and that both PLD1 and PLD2 act synergistically, or partially redundantly, in regulating thrombosis-relevant events, including acute pulmonary thrombosis and ischemic stroke, in mice." (PMID 32971863, 2020). "Likewise, only PLD1 inhibition, but not PLD2 inhibition, could partially improve ischemic stroke, and inhibition of both PLD1 and PLD2 could afford considerable protection against ischemic stroke." (PMID 32971863, 2020).
lung carcinoma (4 papers, 2011 to 2021). "High levels of PLD1 activity have been shown in T24 bladder and Calu-1 lung cancer cells that harbor mutations in H-Ras and K-Ras, respectively." (PMID 21714887, 2011). "We observed that the mRNA level of ALDOA is positively correlated with PLD1, which is consistent with our findings in lung cancer." (PMID 35127525, 2021). "Merging this evidence, we demonstrated that ALDOA and PLD1 coordinately endow lung cancer cells with resistance to alkylating agents and radiation." (PMID 35127525, 2021). "We first treated the lung cancer cell line A549 with alkylating drugs (cisplatin or temozolomide) to simulate the previous in silico dataset, then added PLD1/PLD2 inhibitors, respectively." (PMID 35127525, 2021). "The IHC results demonstrated that the level of PLD1 protein in patients with lung cancer was elevated." (PMID 35127525, 2021). "At the same time, along with alkylating agents or radiation exposure, ALDOA and PLD1 jointly support various aggressive cancer phenotypes and the metabolic reprogramming of lung cancer cells." (PMID 35127525, 2021). "Our data confirm that ALDOA can coordinate with PLD1 by regulating the RNA levels of lung cancer patients." (PMID 35127525, 2021). "Most importantly, the combination of ALDOA and PLD1 can be used as an independent prognostic factor and is correlated with several clinical parameters in lung cancer." (PMID 35127525, 2021). "Our research not only proves that the regulation of phospholipase D depends on PLD1 in lung cancer, but it also shows that ALDOA is required as a gatekeeper for glycolytic conversion and intermediate production." (PMID 35127525, 2021). "The data indicated that the ALDOA and PLD1 protein levels were positively correlated with the relatively poor overall and disease-free survival rates among lung cancer patients." (PMID 35127525, 2021). "We currently speculate that PLD1 can dominate lung cancer metastasis and supplement the production of PA after the function of PLD2 is attenuated or even more, but this requires further research." (PMID 35127525, 2021). "Furthermore, a high expression of aldolase A combined with PLD1 synergistically indicated a poor survival rate in lung cancer patients, consistent with the cell model." (PMID 35127525, 2021). "Most importantly, ALDOA and PLD1 have predictive value for the survival of lung cancer patients." (PMID 35127525, 2021). "Therefore, we claim the ALDOA/PLD1 axis as an independent prognostic factor for lung cancer." (PMID 35127525, 2021). "In this study, we provide evidence that ALDOA directly binds to PLD2 to suppress its specific enzymatic activity, resulting in an increase in PLD1 levels and an increase in total PLD enzyme activity to promote lung cancer cell invasion." (PMID 35127525, 2021). "We examined the expression levels of PLD1 and PLD2 in some lung cancer cell lines (A549 and H460) of the same cohort (GSE116436)." (PMID 35127525, 2021). "Several reports have focused on the PLD1/PLD2 balance and switch in different cancer types; however, there are few reports on lung cancer." (PMID 35127525, 2021). "It is quite possible that DNA sequence variations in PLD1, a gene that has recently been studied for its association with the development of many cancers, may lead to alteration in the activity of PLD, which can cause individual differences in lung cancer susceptibility." (PMID 23675264, 2012). "Thus, ALDOA-PLD1 should be monitored in the future, and targeting the ALDOA/PLD1 axis should be developed as a therapy for lung cancer patients." (PMID 35127525, 2021). "To investigate whether the ALDOA/PLD1 axis has clinical significance for cancer patients, we performed the immunohistochemical (IHC) staining of ALDOA, PLD1, and PLD2 with specific antibodies in clinical lung cancer samples to validate these findings." (PMID 35127525, 2021).
lung carcinoma (continued). "Therefore, we studied the role of PLD1/PLD2 in lung cancer and assessed whether enzyme activity and protein function are involved in lung cancer progression." (PMID 35127525, 2021).
myocardial infarction (4 papers, 2018 to 2020). Gross necrosis of the myocardium, as a result of interruption of the blood supply to the area, as in coronary thrombosis. "After cardiac ischemia and reperfusion (I/R) injury, loss of PLD1 led to increased infarct size and impaired left ventricular function 28 days after myocardial infarction (MI) compared to control mice." (PMID 32370031, 2020). "Indeed, in an experimental model of myocardial infarction, loss of PLD1 leads to defective cell adhesion and migration of inflammatory cells into the infarct border zone, and to altered scar formation resulting in enhanced infarct size and declined myocardial function." (PMID 33114406, 2020). "Thus, PLD1 plays a role in thrombo-inflammatory processes known to aggravate organ damage following ischemia/reperfusion injury after ischemic stroke and myocardial infarction." (PMID 33114406, 2020). "Moreover, PLD1 plays a pivotal role in Tumor Necrosis Factor-alpha (TNF-α) mediated inflammation and scar formation after acute myocardial infarction in mice." (PMID 29968773, 2018).
neuroblastoma (4 papers, 2014 to 2023). Neuroblastoma (NB) is the most common solid, extracranial childhood tumor. "To validate the involvement of PLD1 in calcium dysregulation we used CRISPR technology to knockdown PLD1 in the SH-SY5Y neuroblastoma cell line." (PMID 37426342, 2023). "Furthermore, PLD1 controls autophagic flux and clearance of α-syn aggregates, whereas overexpression of wild-type α-syn in human neuroblastoma cells reduces PLD1 expression." (PMID 35912090, 2022). "Moreover, phospholipase D1 regulates the autophagic flux and clearance of alpha-synuclein aggregates, while the overexpression of wild-type α-syn in human neuroblastoma cells inhibits the PLD1 expression." (PMID 34299248, 2021).
pneumonia (4 papers, 2014 to 2022). An acute, acute and chronic, or chronic inflammation focally or diffusely affecting the lung parenchyma, caused by an infection in one or both of the lungs (by bacteria, viruses, fungi, or mycoplasma.). "We have recently demonstrated that pld1 encodes a virulence factor essential in the pneumonia mouse model." (PMID 32191774, 2020). "One gene, pld1, was shown to be involved in virulence in a mouse model of pneumonia and revealed a novel implication of lipid metabolism in K. pneumoniae pathogenesis." (PMID 24885329, 2014). "The pld1 mutant was avirulent in a pneumonia model in mouse." (PMID 24885329, 2014). "Furthermore, in a hypervirulent strain Kp52.145, another T6SS effector gene pld1, encoding a phospholipase D family protein (PLD1), located within the T6SS locus, was reported as a virulence factor, exhibiting that Δpld1 was avirulent in comparison to wild-type in a mouse model of pneumonia." (PMID 33897652, 2021).
viral infections (4 papers, 2015 to 2023). "Therefore, PLD1 participates in bacterial and viral infectious diseases; however, the mechanism underlying the Vu0155069 effect on caspase-1 activity is unclear." (PMID 37381714, 2023). "The marked increases in Ccr2, Ccr5, Pld1, and Ackr3 produced by either AMPH or EIH observed in vivo provide further insight into the initial immune system alterations that result from methamphetamine and AMPH abuse and could modify risk for HIV and other viral infections." (PMID 30779732, 2019).
colon cancer (3 papers, 2010 to 2014). "A mutation of Ras resulted in increased levels of PLD1 mRNA in colon cancer cells and the mutated-Ras interacts with PLD1 via the Sp1 transcription factor." (PMID 24103483, 2014). "Among one of the genes identified in this screen was PLD1, and suppression of PLD1 significantly inhibited both β-catenin transcriptional activity and colon cancer cell proliferation." (PMID 20711340, 2010). "The PLD1-PH also reduced proliferation of colon cancer cells relative to the control." (PMID 25361009, 2014).
dyslipidemia (3 papers, 2010 to 2023). "Phospholipase families of PLD2 and PLD1 were determined as targets for dyslipidemia and can activate MAPK." (PMID 36295794, 2022).
hepatocellular carcinoma (3 papers, 2019 to 2022). A malignant tumor that arises from hepatocytes. "High PLD1 expression is frequently detected in various cancers, including glioma, pancreatic ductal adenocarcinoma, colorectal cancer, hepatocellular carcinoma, breast cancer, and melanoma." (PMID 30970654, 2019). "Similarly, inhibition of PLD1 suppresses cancer cell biological functions in prostate cancer, hepatocellular carcinoma and bladder cancer." (PMID 35775110, 2022). "Previous studies demonstrated that inhibition of PLD1 could attenuate tumour EMT in hepatocellular carcinoma mice, and PLD1 mediated EMT in hepatocellular carcinoma." (PMID 35775110, 2022).
HIV-1 infection (3 papers, 2015 to 2024). The type species of lentivirus and the etiologic agent of acquired immunodeficiency syndrome (AIDS). "PLD1 inhibition of HIV-1 infection was partially rescued by adding exogenous deoxyribonucleosides that bypass the need for de novo dNTP synthesis." (PMID 26020637, 2015). "Ackr3, Pld1, and Ccr2 expression up-regulation had patterns very similar to Ccr5 and further indicate that AMPH and EIH can exacerbate HIV-1 infection." (PMID 30779732, 2019).
lung adenocarcinoma (3 papers, 2012 to 2023). A carcinoma that arises from the lung and is characterized by the presence of malignant glandular epithelial cells. "Furthermore, activation of PLD1 by bradykinin and sphingosine 1 is involved in the protein kinase C signaling pathway in A549 human lung adenocarcinoma cells, suggesting a possible association between PLD1 and NSCLC." (PMID 23675264, 2012). "Furthermore, the activation of PLD1 by bradykinin and sphingosine 1 is involved in the PKC signaling pathway in A549 human lung adenocarcinoma cells, indicating an association between PLD1 and NSCLC." (PMID 37370855, 2023).
prostate carcinoma (3 papers, 2021 to 2023). A carcinoma that arises from epithelial cells of the prostate gland. "PLD1 has been linked with prostate cancer proliferation and colony formation." (PMID 34238129, 2021). "Therefore, PLD1 downregulation by wt-ANXA7 could mediate its cell elimination effects (especially in prostate cancer)." (PMID 37240163, 2023).
Arthritis (2 papers, 2020 to 2023). Inflammation of a joint. "Additionally, genetic and pharmacological inhibition of PLD1 can cause suppression of collagen-induced arthritis symptom, such as induction of the inflammatory response, bone destruction, and osteoclastogenesis." (PMID 36855165, 2023). "This arthritis-associated Th17/Treg cell imbalance was rescued by the PLD1 inhibitor." (PMID 32370217, 2020). "The PLD1 inhibitor delayed the onset of arthritis and decreased the incidence of arthritis, arthritic score, and the number of affected limbs." (PMID 32370217, 2020). "As analyzed by the arthritis score and incidence, PLD1+/+ DBA1/J mice developed signs of arthritis following immunization." (PMID 32370217, 2020). "Here, we demonstrate that targeting PLD1 effectively ameliorates arthritis in CIA mice, and thus, PLD1 may contribute to joint inflammation in RA." (PMID 32370217, 2020). "Reduction in IgG2a levels by targeting PLD1 might ameliorate the severity of arthritis, suggesting a potential role of PLD1 in B cells." (PMID 32370217, 2020). "However, the joints of CIA-challenged PLD1−/− mice showed reduced progression of CIA compared with that in the joints of PLD1+/+ mice, suggesting that PLD1 promotes disease severity in arthritis." (PMID 32370217, 2020).
cardiomyopathies (2 papers, 2023 to 2025). "Recessive PLD1 variants also correlatewith isolated neonatal cardiomyopathies." (PMID 37808210, 2023). "This includes a recent report of biallelic inheritance of two recessive phospholipase D1 (PLD1) loss-of-function variants leading to right-sided valvular disease and cardiomyopathy." (PMID 40438121, 2025).
cognitive decline (2 papers, 2019 to 2023). "In the present study, we first established the scientific premise of PLD1 as a key element associated with progressive cognitive decline using human clinical samples." (PMID 36834781, 2023). "Collectively, these studies provide evidence for inhibition of PLD1 as a potential therapeutic strategy in preventing progression of cognitive decline associated with AD and related dementia." (PMID 31797996, 2019). "This increases the enthusiasm in the potential therapeutic application of PLD1 inhibitor in preventing AD-related cognitive decline." (PMID 31797996, 2019). "Moreover, our systematic functional studies established that increased PLD1 promotes synaptic vulnerability and can exacerbate oligomeric (AβO- and TauO-) amyloidogenic cognitive decline." (PMID 36834781, 2023). "Our follow-up study investigated the scientific premise of progressive Aβ accumulation in 6-month-old 3xTg-AD mice expressing elevated PLD1, and more importantly, established PLD1 inhibition as a viable therapeutic target in mediating cognitive decline against Aβ." (PMID 36834781, 2023). "The specificities of reduction could suggest a possible feedback loop between PLD1, Aβ and tau that results in the preservation of dendritic spines, restoration of synaptic function and prevention of cognitive decline." (PMID 36834781, 2023). "Thus, in this study, we addressed whether chronic PLD1 inhibition in the later stages of AD-like neuropathology, that has a greater dependence on tau, is still sufficient to provide resistance to the progression of cognitive decline." (PMID 36834781, 2023). "Perhaps repeated PLD1 inhibition at 1 mg/kg may be optimal in modulating glutamatergic neurotransmission to preserve synaptic functionality, thereby altering the homeostasis enough to resist cognitive decline without affecting the physiological functionality associated with Aβ and tau." (PMID 36834781, 2023).
colitis (2 papers, 2022 to 2024). Inflammation of the colon. "Targeting PLD1 in ApcMin/+ and colitis-associated CRC mice decreases the level of nuclear β-catenin but not membrane-associated β-catenin, which is detected both in the nontransformed areas of the intestines and in the normal areas of ApcMin/+ mice." (PMID 38945955, 2024). "The PLD1 inhibitor attenuated colitis-associated CRC and orthotopically injected tumors, probably by controlling multiple pathways, including Wnt signaling, phagocytosis checkpoint, and immune signaling pathways." (PMID 38945955, 2024). "Collectively, these results suggest that the inhibition of PLD1 attenuates colitis-associated CRC, probably by controlling multiple pathways, including Wnt signaling, phagocytosis checkpoints, and immune signaling." (PMID 36131027, 2022). "Targeting PLD1 attenuates spontaneous and colitis-associated intestinal tumorigenesis." (PMID 38945955, 2024). "Moreover, PLD1 inhibition attenuated colitis-associated CRC and orthotopically injected tumors, probably by controlling multiple pathways, including Wnt signaling, phagocytosis checkpoints, and immune signaling." (PMID 36131027, 2022).
deep vein thrombosis (2 papers, 2018 to 2025). "In vivo, PLD1-deficient mice fail to generate ROS in an acute lung inflammation model and are protected from venous thrombosis." (PMID 41194921, 2025). "In vivo, PLD1 deficiency resulted in loss of ROS production in the lung following lipopolysaccharide (LPS) challenge, and significantly attenuated deep vein thrombosis (DVT), a NET-associated pathology." (PMID 41194921, 2025). "To examine whether PLD1 deficiency impacts thrombus development, we employed a well-established murine model of deep vein thrombosis (DVT) involving partial flow restriction (stenosis) of the inferior vena cava (IVC)." (PMID 41194921, 2025). "Furthermore, PLD1 deficient mice are protected against arterial thrombosis because PLD1 is important for integrin αIIbβ3-mediated platelet activation and thrombus formation under high shear conditions." (PMID 29968773, 2018). "In vivo, PLD1-deficient mice exhibited impaired ROS production in the lungs following LPS challenge, despite normal neutrophil recruitment, and were protected from deep vein thrombosis (DVT) after IVC stenosis." (PMID 41194921, 2025). "Accordingly, Pld1−/− mice are protected against arterial thrombosis and ischemic brain infarction." (PMID 29968773, 2018). "Moreover, direct comparison of PLD1 and PLD2 in the same thrombosis model will be important to clarify isoform specificity and potential redundancy." (PMID 41194921, 2025).
Disseminated intravascular coagulation (2 papers, 2018 to 2020). Disseminated intravascular coagulation is characterized by the widespread activation of coagulation, which results in the intravascular formation of fibrin and ultimately thrombotic occlusion of small and midsize vessels. "Furthermore, reduced thrombin generation of PLD1 deficient platelets might be responsible for reduced fibrin formation in lungs suggesting reduced disseminated intravascular coagulation (DIC)." (PMID 29968773, 2018).
fibrosarcoma (2 papers, 2020 to 2024). A malignant mesenchymal fibroblastic neoplasm affecting the soft tissue and bone. "Phospholipase D (PLD1 & 2) activity increases blebbing in Fibrosarcoma." (PMID 39222238, 2024). "The small molecule inhibitor 5-fluoro-2-indolyl des-chlorohalopemide (FIPI), blocks PLD1 and PLD2 activity, effectively suppressing bleb formation in the HT1080 Fibrosarcoma cell line." (PMID 39222238, 2024).